LDAF1 (lipid droplet assembly factor 1)
Description:
Plays an important role in the formation of lipid droplets during the differentiation and maturation of adipocytes. Together with seipin (BSCL2), defines the sites of lipid droplet formation in the endoplasmic reticulum and promotes the aggregation of triacylglycerol molecules to form the core of a lipid droplet (nucleation) in the endoplasmic reticulum and drive budding of lipid droplets into the cytoplasm.
Synonyms: TMEM159; promethin
Tractability: Antibody: UniProt predicts a signal peptide or a membrane-spanning region. PROTAC: ubiquitination databases record sites on it.
Gene: Protein-coding gene on chromosome 16 (21,158,305 to 21,181,330, forward strand). Ensembl gene ENSG00000011638.
Subcellular location: Endoplasmic reticulum membrane; Lipid droplet
Subcellular location (Human Protein Atlas): Vesicles
Gene Ontology:
Molecular function: protein binding
Biological process: lipid droplet formation
Cellular component: endoplasmic reticulum membrane; lipid droplet
Genetic constraint (gnomAD): Loss-of-function variants: 7 observed, 12.68 expected, observed/expected ratio (o/e) 0.55, 90% interval 0.31 to 1.04. The upper end of that interval is the gene's LOEUF score, 1.04, which puts it in group 4 of 6, group 1 being the genes least tolerant of losing a copy. Missense variants: 135 observed, 180.4 expected, observed/expected ratio (o/e) 0.75, 90% interval 0.65 to 0.86. Synonymous variants: 61 observed, 73.66 expected, observed/expected ratio (o/e) 0.83, 90% interval 0.67 to 1.02.
Homologues: Orthologues: chimpanzee LDAF1 (98% identical), macaque LDAF1 (89% identical), rabbit LDAF1 (77% identical), guinea pig LDAF1 (70% identical), pig LDAF1 (70% identical), mouse Ldaf1 (70% identical), rat Ldaf1 (70% identical), tropical clawed frog ldaf1 (38% identical).